SLC6A14 (solute carrier family 6 member 14)
Diseases named in the same sentence as SLC6A14 in open-access papers (continued):
Sharing a sentence is not in itself a finding about the gene and the disease.
pancreatic cancer (19 papers, 2015 to 2025). "The findings of amino acid starvation in pancreatic cancer cells are associated with reduced growth and proliferation after pharmacological inhibition of SLC6A14." (PMID 33198082, 2020). "Several reports have shown that the over-expression of SERPINB5 (serine protease inhibitor B5) can promote PDAC metastasis, and the marked up-regulation of SLC6A14 (solute carrier, family 6, member 14) in pancreatic cancer leads to worse survival." (PMID 40362181, 2025). "To date, the expression of SLC6A14 is upregulated in estrogen receptor-positive breast cancer, cervical cancer, pancreatic cancer, and colorectal cancer." (PMID 35907820, 2022). "SLC6A14 involvement in cell proliferation has also been shown in other cancer cells such as pancreatic cancer cells." (PMID 35372502, 2022). "In pancreatic cancer, the clinical potential of an amino acid transporter SLC6A14 as a drug target has been recently reported." (PMID 34123356, 2021). "SLC6A14 has been investigated as a potential novel therapeutic target for pancreatic cancer using α-methyltryptophan as a pharmacological inhibitor of SLC6A14 and showed reduced proliferation and clonogenic survival." (PMID 32024004, 2020). "Based on the data from Protein Atlas2 survival prognosis at either low or high SLC6A14 expression level was found prognostic for pancreatic cancer, being unfavorable at high SLC6A14 expression, although the cohorts were relatively small." (PMID 33195271, 2020). "Further experiments with pancreatic cancer cell lines treated with shRNA showed that SLC6A14 knock-down decreased the invasion of cancer cells, as measured in the transwell assay." (PMID 33195271, 2020). "Experiments performed with pancreatic cancer cells characterized by various SLC6A14 expression level showed that treatment with α - MT - SLC6A14 blocker, led to amino acid starvation of cells with high SLC6A14." (PMID 33195271, 2020). "Therapeutic strategies targeting SLC6A14, either alone or in combination with PD-L1 blockade, hold promise for overcoming chemoresistance and enhancing antitumor immunity in gemcitabine-resistant pancreatic cancer." (PMID 41444422, 2025). "Therefore, the present study provides evidence for a new potential use of alloferon and gemcitabine for the treatment of pancreatic cancer by the regulation of SLC6A14 expression." (PMID 35625849, 2022). "Pancreatic tumors in KPC mice show evidence of Slc6a14 up-regulation." (PMID 35212370, 2022). "This upregulation of SLC6A14 in pancreatic cancer makes it not only a good candidate as a marker but may make it a drugable target." (PMID 33195271, 2020). "This highlighted SLC6A14 as a potential prognostic biomarker of pancreatic cancer." (PMID 32024004, 2020). "Another study analyzing differentially expressed genes in pancreatic cancer also detected SLC6A14 among the top ten upregulated genes and survival analysis of seven of these genes (TMPRSS4, SERPINB5, SCEL SCL6A14, TMC7, SLC2A1, CENPF) is associated with patient poor prognosis." (PMID 33195271, 2020). "Gene expression omnibus database analysis showed 13- to 163-fold increase of SLC6A14 expression in pancreatic tumors, when compared with normal pancreatic tissue, an increase much higher than the increase of expression of other amino acid transporters: SLC1A5, SLC7A5, SLC7A11." (PMID 33195271, 2020). "Amino acid transporter, SLC6A14, might represent a possible therapeutic target for pancreatic cancer, and it was found to be upregulated in patient-derived xenografts and primary pancreatic tumors, as well as colorectal cancer." (PMID 31447885, 2019). "For this analysis, we used a pancreatic cancer TMA and immunohistochemistry with an antibody against SLC6A14." (PMID 26106611, 2015).
Obesity (15 papers, 2010 to 2025). Accumulation of substantial excess body fat. "The obesity associated with SLC6A14 loss on a high-fat diet is accompanied with many parameters indicative of metabolic syndrome." (PMID 35204736, 2022). "We have validated the cause–effect relationship between SLC6A14 deficiency and increased food intake/obesity with evidence that SLC6A14-null mice are at increased risk for diet-induced obesity, fatty liver and metabolic syndrome." (PMID 35204736, 2022). "A specific genetic polymorphism in the SLC6A14 gene, though present in a non-coding region, suppresses the expression of the gene, and this polymorphism correlates with obesity." (PMID 35204736, 2022). "Deletion of SLC6A14 in mice confirmed that SLC6A14 loss leads to diet-induced obesity/metabolic syndrome and fatty liver." (PMID 35204736, 2022). "It is worth mentioning that using a similar method, a recent report has shown that the obesity-associated SLC6A14 rs2011162 SNP also reduced SLC6A14 expression." (PMID 35372502, 2022). "Obesity is often associated with a wide spectrum of liver abnormalities; this is also true with obesity, as seen in SLC6A14-null mice on a high-fat diet." (PMID 35204736, 2022). "It was proposed that this association with obesity resulted from availability of a SLC6A14 substrate – Trp, a precursor of serotonin, which controls appetite." (PMID 33195271, 2020). "Interestingly, two studies in Finnish and French showed that several SLC6A14 variants were associated with obesity." (PMID 35207740, 2022). "Pathway analysis by Reactome confirmedall dysmetabolism individuated to pathway analysis by MetaboAnalyst4.0 and has shown a possible link to SLC6A14 genevariations that may be associated with obesity." (PMID 33164516, 2021). "Interestingly, single nucleotide polymorphism (SNP) in the 3′-untranslated region of SLC6A14 gene was associated with obesity of Finnish population." (PMID 33195271, 2020). "SLC6A14 genetic variants have been associated with obesity in different populations." (PMID 32166393, 2020). "Reported associations between human obesity and genomic markers in a related neutral amino acid transporter, SLC6A14, support the idea that human variations in other neutral amino acid transporters might also play significant roles in obesity-related traits." (PMID 24023709, 2013). "Finally, an in vitro study highlighted that the obesity-associated rs2011162 variant, located in the 3′UTR of the SLC6A14 gene, reduces the expression of the transporter and that Slc6a14−/− mice develop obesity, fatty liver and metabolic syndrome when fed with a high-fat diet." (PMID 35207740, 2022). "Genes implicated in monogenic obesity include POMC, LEP, LEPR, MC3R, and MC4R, while polygenic obesity involves variants in genes such as FTO, UCP1-3, MC4R, ADRB1-3, and SLC6A14." (PMID 41302083, 2025). "We have shown that the obesity-associated SNP, present in the 3′-UTR of SLC6A14 mRNA, decreases the expression of the transporter protein." (PMID 35204736, 2022). "The recent discovery of the role of SLC38A5 in promoting macropinocytosis and the contrasting roles of SLC6A19 and SLC6A14 in diet-induced obesity and metabolic syndrome highlights these novel and unconventional functions of specific amino acid transporters." (PMID 35204736, 2022). "In the present review, we highlight the unusual involvement of selective amino acid transporters in macropinocytosis (SLC38A5/SLC38A3) and diet-induced obesity/metabolic syndrome (SLC6A19/SLC6A14/SLC6A6)." (PMID 35204736, 2022). "However, there are reports on six of Slc genes (Slc2a10, Slc5A1, Slc5a9, Slc6A14, Slc16A5, Slc25A24) in metabolic diseases including obesity, dyslipidemia, NAFLD, and T2DM." (PMID 34659115, 2021). "The molecular mechanisms underlying the obesity in SLC6A14-null mice are not known." (PMID 35204736, 2022).
Obesity (continued). "In our recent study, α-MT was found to reduce food intake and body weight in multiple models of diet-induced obesity by a mechanism that is independent of its ability to block SLC6A14." (PMID 39902076, 2024). "Deletion of SLC6A14 in mice does not lead to significant detrimental consequences under normal conditions, even though the null mice are resistant to certain cancers and also are prone to obesity when fed a high-fat diet." (PMID 39902076, 2024).
colorectal cancer (13 papers, 2019 to 2025). A primary or metastatic malignant neoplasm that affects the colon or rectum. "Beyond CAT1, SLC6A14—a protein with low expression in normal tissues—serves as a Wnt target and its expression level is strongly correlated with colorectal cancer." (PMID 41488637, 2025). "High SLC6A14 expression in colorectal cancer promotes cancer cell survival and metastasis by enhancing arginine uptake." (PMID 41488637, 2025). "Combination of SLC6A14 with SLC1A5 or SLC38A5 had a larger effect in breast versus colorectal cancer cell lines, likely reflecting that tissue of origin can influence SLC substrate selectivity." (PMID 38066114, 2023). "Collectively these results suggest that SLC6A14 has the ability to transport a range of amino acids and functions as a major serine transporter in the studied colorectal cancer cells." (PMID 38066114, 2023). "Apart from PDAC, SLC6A14 is also significantly up-regulated in colorectal cancer, estrogen receptor (ER)-positive breast cancer, and cervical cancer." (PMID 35212370, 2022). "The JAK2/STAT3 signaling pathway mediates the function of solute carrier family 6 member 14 (SLC6A14) to promote the proliferation and metastasis of colorectal cancer cells." (PMID 34895038, 2021). "Arginine transporter CAT-1 and Human member 14 of the solute carrier family 6 (SLC6A14) are overexpressed in colorectal cancer cells and contributes to intracellular arginine levels." (PMID 34095122, 2021). "Likewise, literature evidence shows similar findings in colorectal cancer and ER-positive breast cancer, further establishing SLC6A14 as a tumor promoter and a potential drug target for cancer therapy." (PMID 35212370, 2022). "In addition, several enzymes and transport molecules in the arginine metabolic pathway such as ODC, CAT, and SLC6A14 were involved in the development of tumors, including colorectal cancer." (PMID 34095122, 2021). "However, little is known about the roles of SLC6A14 in colorectal cancer (CRC)." (PMID 35907820, 2022). "Dual targeting of SLC6A14 and either SLC25A15 or SLC12A4 diminishes serine uptake and growth of colorectal cancer cells in vitro and in vivo, particularly in cells with compromised de novo serine biosynthesis." (PMID 38066114, 2023). "The expression of solute carrier family 6 member 14 (SLC6A14), also known as amino acid transporter B0,+, is upregulated in active UC and colorectal cancer." (PMID 35959356, 2022).
lung disease (11 papers, 2015 to 2024). "We confirm that SLC6A14 rs3788766 SNP is associated with lung disease severity in pwCF (p = 0.020; n = 3,257, pancreatic insufficient, aged 6–40 years old), with the minor allele G being deleterious." (PMID 35372502, 2022). "Among these, the gene encoding for the amino acid transporter SLC6A14 has been associated with lung disease severity and age of primary airway infection by the bacteria Pseudomonas aeruginosa." (PMID 35372502, 2022). "Genotype-phenotype association study between lung disease severity and SLC6A14 rs3788766 genotypes, in 3,257 patients with cystic fibrosis." (PMID 35372502, 2022). "The allelic variant rs7512462 of the SLC26A9 gene has a pleiotropic effect and is associated with both pancreatic disease and MI, while variant rs3788766 (SLC6A14) is correlated with MI, lung disease, and the age of onset of P. aeruginosa infection." (PMID 34945117, 2021). "Their results showed that SLC6A14 mRNA expression in CF nasal epithelia and in the pancreas colocalize with the lung disease and MI-associated variants, respectively, suggesting that each locus impacts SLC6A14 expression with tissue specificity." (PMID 32166393, 2020). "Among the identified loci, one locus on chromosome X, near the SLC6A14 gene, was associated with a variability in the severity of CF clinical manifestations including lung disease severity/pulmonary infections or presence of MI/onset of digestive symptoms." (PMID 32166393, 2020). "further assessed the association of MI risk alleles of SLC6A14 with other CF co-morbidities, such as the lung disease severity and age at first P. aeruginosa infection." (PMID 32166393, 2020). "The SLC6A14 eQTLS from the nasal epithelia (blue dashed line) and pancreas (black solid line) tissues appeared to coincide, respectively, with lung disease and meconium ileus associated variants." (PMID 30807572, 2019). "In this study, we investigated whether the single nucleotide polymorphism (SNP) rs3788766, located within SLC6A14 promoter, is associated with lung disease severity in a large French cohort of pwCF." (PMID 35372502, 2022). "In a large cohort of pwCF (n = 6,365), we previously identified five CF lung disease modifier loci by genome-wide association studies (GWAS), including one containing the solute carrier family six member 14 gene (SLC6A14, also known as ATB0,+)." (PMID 35372502, 2022). "Indeed, the authors found a significant association between genotypes of three SLC6A14 intergenic variants (rs7879546, rs5905376, and rs5952223) and the lung disease severity." (PMID 32166393, 2020). "Furthermore, genetic studies highlight that SLC6A14 genetic variants modulate the severity of digestive and pulmonary diseases in CF patients." (PMID 32166393, 2020). "Using the SS we integrated the lung disease association locus with eQTLs from nasal epithelia of 63 CF participants and demonstrated evidence of colocalization with airway-specific regulation of SLC6A14 (p = 2.3x10-4)." (PMID 30807572, 2019). "The SLC6A14 gene has pleiotropic effects in pwCF, with several SLC6A14 single nucleotide polymorphisms (SNPs) being associated with different phenotypes such as meconium ileus (MI) occurrence, a severe neonatal intestinal obstruction, lung disease severity, and age at first P. aeruginosa infection." (PMID 35372502, 2022). "To conclude, we confirmed that SLC6A14 rs3788766 genotype influences the lung disease severity of pwCF." (PMID 35372502, 2022). "Some of these known modifiers are ranked within the top DPMs, including EHF, SFTPA2, and SLC6A14, all previously identified modifiers of lung disease severity in CF." (PMID 33438800, 2020). "SLC6A14 has been identified as a genetic modifier of multiple CF disease outcomes, including meconium ileus, lung disease and the age of first infection by Pseudomonas aeruginosa." (PMID 30004386, 2018).
lung disease (continued). "To conclude, our study highlights that SLC6A14 genotype might affect lung disease severity of people with cystic fibrosis via mTOR and epithelial repair mechanism modulation in the lung." (PMID 35372502, 2022). "The chrX locus contains AGTR2 and SLC6A14 and either gene, or possibly both, could modify lung disease." (PMID 26417704, 2015). "Moreover, genome-wide association studies has recently identified SLC6A14/ATB0,+ as a genetic modifier of lung disease severity in cystic fibrosis, providing a mechanism by which it regulates Pseudomonas aeruginosa attachment to human bronchial epithelial cells." (PMID 32027707, 2020). "Given sub-optimal content of epithelia in the GTEx lung tissue samples by design, we calculated SLC6A14 eQTLs from the CF nasal epithelia which provided colocalization evidence with the lung disease associated variants(p = 2.4x10-4); AGTR2 was not expressed in the nasal epithelia." (PMID 30807572, 2019).
colon cancer (10 papers, 2014 to 2025). "Treatment of colon cancer cells with α-methyltryptophan (α-MT), a blocker of SLC6A14, decreases mTOR activity, triggers autophagy and promotes apoptosis." (PMID 37373349, 2023). "Recently, researchers have paid attention to the evaluation of the impact of SLC6A14 deletion on colon cancer in multiple preclinical model systems, comparing the effects with pharmacologic SLC6A14 blockade." (PMID 37373349, 2023). "SLC6A14 was upregulated in colon tumors, whereas there was lower expression in breast tumors but with high variance in that group." (PMID 38066114, 2023). "Chromatin immunoprecipitation confirmed that SLC6A14 is the target of β-catenin, SLC6A14 can regulate autophagy, plays a key role in promoting colon cancer, and its upregulation in cancer involves Wnt signaling." (PMID 35836256, 2022). "This interplay between SLC6A14 and mTOR was also recently confirmed in colon cancer LS174T cell line treated with α-MT." (PMID 35372502, 2022). "Transcription factor TCF4 (T-cell factor 4) is known to be indispensable for tumor initiation and TCF4/β-catenin transcriptional activity mediated by Wnt signaling was proposed to control upregulation of SLC6A14 in colon cancer." (PMID 33195271, 2020). "The deletion of Slc6a14 protected mice from colon cancer, while it’s silencing or blocking with its specific blocker - α-methyltryptophan (α-MT) led to a reduced tumor growth and suppressed proliferation due to autophagy and apoptosis." (PMID 33195271, 2020). "Recently, the upregulation of SLC6A14 was reported in most human colon cancer cell lines and in a majority of patient-derived xenografts." (PMID 33195271, 2020). "As SLC6A14 is involved in colon cancer cell proliferation, migration, and invasion, we wondered whether it could play a role in bronchial epithelial repair, a process which involves both cell proliferation and migration mechanisms." (PMID 35372502, 2022). "Studies published thus far established that SLC6A14, a Na+/Cl− coupled neutral and cationic amino acid transporter, is up-regulated in CRC tissues and in colon cancer cell lines." (PMID 37373349, 2023). "In colon tumor tissue, similar gene expression changes were found for CYR61, RGS1, DUSP1, DUOX2, and SLC6A14, although the log-fold change was generally lower compared to normal tissue." (PMID 25526028, 2014).
ulcerative colitis (8 papers, 2013 to 2025). An inflammatory bowel disease involving the mucosal surface of the large intestine and rectum. "SLC6A14 is highly upregulated in ulcerative colitis and also in solid tumours including breast, colon, liver and pancreatic tumours." (PMID 40121360, 2025). "In addition, SLC26A2 and SLC6A14 mRNA levels have been used as part of a seven gene panel yielding rates of correct prediction, sensitivity, and specificity higher than that with previously available diagnostic indices for ulcerative colitis, Crohn's disease, and irritable bowel syndrome." (PMID 23658834, 2013). "SLC6A14, which imports all neutral amino acid and the two cationic acid lysine and arginine into the cytoplasm, is upregulated in various colonic diseases, including ulcerative colitis." (PMID 39218897, 2024). "After merging and filtering across datasets, 13 genes were found to be consistently upregulated in both ulcerative colitis and type 2 diabetes, with CXCL9, S100A8, CXCL10, CHI3L1, and SLC6A14 showing the most significant alterations." (PMID 41155631, 2025). "SLC6A14 negatively regulates PAK6 in a manner dependent on CCAAT enhancer binding protein beta (C/EBPβ), promoting epithelial cell ferroptosis in ulcerative colitis via the C/EBPβ–PAK6 axis." (PMID 39218897, 2024). "SLC6A14 was also proposed to take over the defective OCTN2 and to mediate transport of butyryl-L carnitine, a compound used for treatment of ulcerative colitis." (PMID 33195271, 2020).
cervical cancer (7 papers, 2014 to 2023). A primary or metastatic malignant neoplasm involving the cervix. "The SLC6A14 gene, a sodium/chloride-dependent neutral and cationic AAs transporter, was strongly overexpressed in several tumor types, including colorectal, gastric, pancreatic, breast, and cervical cancers." (PMID 37397501, 2023).